USP7 (ubiquitin specific peptidase 7)
Diseases named in the same sentence as USP7 in open-access papers (continued):
Sharing a sentence is not in itself a finding about the gene and the disease.
tumor (continued). "Not only USP7 inhibitors but also USP8 inhibitors are involved in regulating anti-tumor immunity." (PMID 39223632, 2024). "Functionally, USP7 exerts multifaceted regulatory effects in tumor inflammation." (PMID 39767641, 2024). "USP7‐dependent fibroblast‐derived VEGF promotes tumour cell growth and survival." (PMID 38602256, 2024). "Inhibiting USP7 suppresses Treg activity, thereby enhancing anti-tumor immunity." (PMID 39223632, 2024). "In addition, USP7 also plays a key role in the regulation of neurological diseases, immune responses, the regulation of tumor-related signaling pathways, and the consequences of inflammatory diseases." (PMID 39767641, 2024). "Multiple studies have indicated that the regulatory effect of USP7 on PD-L1 expression is complex and may depend on the tumor microenvironment." (PMID 39748950, 2024). "In addition, the gene expression level of PRMT1 and USP7 in several tumor types was analyzed by TIMER2.0 network tool." (PMID 39009589, 2024). "Although existing studies suggest that inhibitors of USP7 can suppress the proliferation and survival of tumor cells, thereby inhibiting the occurrence and development of tumors, no highly efficient and safe inhibitors against USP7 have been developed at present." (PMID 39767641, 2024). "Moreover, we established xenograft tumor models by subcutaneously transplanting HCT116 cells with stable knockdown of USP7, YY1, or both into BALB/c nude mice." (PMID 38769122, 2024). "In summary, USP7 plays diverse roles in tumor inflammatory responses, including regulating the stability of tumor-related proteins, influencing immune responses, and regulating tumor cell metabolism." (PMID 39767641, 2024). "Consequently, within the realm of tumor inflammation, the operational mechanism of USP7 likely represents a complex and finely tuned network." (PMID 39767641, 2024). "Comparing USP7 KO mice to the control mice, we found a significant reduction in tumor growth." (PMID 38467635, 2024). "In addition, USP7 is also involved in regulating the metabolism and energy balance of tumor cells, which is an important aspect of the tumor inflammatory responses." (PMID 39767641, 2024). "The results showed that overexpression of USP7 promoted NSCLC tumour growth." (PMID 38082439, 2023). "Additionally, a USP7 inhibitor, P5091, has shown a synergistic anti-tumor effect with a PD-1 inhibitor in vivo." (PMID 37415977, 2023). "We have previously shown that the deubiquitinating enzyme USP7 is a tumor-specific WNT activator in APC-truncated cells by deubiquitinating and stabilizing β-catenin, but its role in gut tumorigenesis is unknown." (PMID 36669491, 2023). "Moreover, DUBs like USP22 play a role in promoting tumor development through the regulation of epigenetic changes, while others such as USP28 and USP7 are involved in controlling the turnover of oncogenes or tumor suppressors." (PMID 37626927, 2023). "In chemical biology studies, USP7 is validated as a target of tumor survival." (PMID 37658402, 2023). "Notably, depletion of G3BP2 and USP7 independently retarded tumor growth, but the efficacy of USP7 silencing was rescued by G3BP2 expression." (PMID 36878903, 2023). "Here, we investigate the role of USP7 in tumor development and intestinal homeostasis in vivo." (PMID 36669491, 2023). "USP7 has been revealed to control the anti-tumor immune responses." (PMID 37215134, 2023). "As for Lewis lung carcinoma mice, treatment with the USP7 inhibitor weakened the tumor growth as well as increased the infiltration of M1 macrophages and CD8 + T cells expressing IFN-γ through the mechanism underlying activating the p38 mitogen-activated protein kinase (MAPK) pathway." (PMID 37658402, 2023).
tumor (continued). "However, despite extensive investigation of USP7 inhibitors in the field of tumor therapy, little is known about their application in the treatment of bone-related diseases." (PMID 37199589, 2023). "Furthermore, combing USP7 inhibitors with other immune-modulatory agents or chemotherapy greatly improve DNA damage effect and help tumor cells to overcome therapeutic resistance." (PMID 37658402, 2023). "Moreover, USP7 inhibitor sensitizes tumor cells to chemotherapeutic agents by decreasing SAMHD1 in vitro and in vivo." (PMID 37081042, 2023). "Moreover, USP7 regulates numerous proteins that function in immune response, tumor generation, tumor suppression, epigenetics, DNA damage, and several signaling pathways." (PMID 35948545, 2022). "Moreover, USP7 suppression downregulated c-Myc, thus inhibiting the tumor cycle and EMT signaling in HCC cells transfected with MYH9 plasmids." (PMID 35414777, 2022). "Additionally, the influence of USP7 inhibition on tumor growth was assessed using a mouse model of E7+ TC1 lung adenocarcinoma for which the growth is Treg-dependent." (PMID 36428632, 2022). "Finally, it is noteworthy that P5091-mediated USP7 inhibition resulted in increased PD-L1 expression in tumor cells." (PMID 36428632, 2022). "Patients with MDM2 overexpression and immunosuppressive tumor microenvironment may have the largest benefit from the use of USP7 inhibitors." (PMID 36428632, 2022). "Raised USP7 expression may suggest a poor tumor prognosis; therefore, it has been considered by some researchers to be a marker for prognosis and a potential drug target for anticancer therapy." (PMID 36291159, 2022). "The study showed that the administration of USP7 inhibitors could potentiate the efficacy of tumor vaccine therapy." (PMID 36428632, 2022). "Finally, we decided to further investigate Usp7, Metap1 and Metap2 due to most distinct effects in the first validation assays and literature postulating tumor-promoting functions of these proteases 62-73." (PMID 35673573, 2022). "This suggests that therapeutic USP7 inhibition may reduce the immunosuppressive functions of Tregs within the tumor microenvironment and thereby facilitate the elimination of tumor cells." (PMID 36428632, 2022). "USP7 was shown to regulate the anti-tumor immune responses in several cases." (PMID 36428632, 2022). "As EZH2 is a methyltransferase, EZH2 and USP7 may regulate the levels of methylation and ubiquitination of cGAS, which leads to the production of inflammatory factors in tumor cells after the activation of cGAS." (PMID 35163710, 2022). "USP7 promoted cell proliferation, migration, invasion in vitro and tumor growth by stabilizing TAZ." (PMID 35931679, 2022).
tumor (continued). "In this review, we proceeded from the structure and function of USP7, further found that USP7 is closely related to tumor resistance, and proposed that targeting USP7 might be a new insight to overcome drug resistance." (PMID 33967786, 2021). "Therefore, aim of the current study is to investigate the molecular mechanism of USP7 in regulating tumor progression and signaling pathways of OSCC and to verify its relationship with Ki-67, MMP2, and VEGF." (PMID 34812471, 2021). "Consistent with our observation that USP7 coordinated with the PRC2 complex is linked to downregulation of FOXO1, we showed that the expression level of FOXO1 is decreased and negatively associated with those of USP7 and EZH2 in various tumor tissue samples." (PMID 33849069, 2021). "And USP7 promotes the packaging of lncFERO into exosomes from GC cells through regulating deubiquitination on hnRNPA1, which ultimately leads to chemo-resistance and tumor progression through the exo-lncFERO/hnRNPA1/SCD1 axis." (PMID 34845198, 2021). "USP7 is currently an important targeted protein for tumor therapy." (PMID 33498168, 2021). "This is accordance with previous reports that USP7 functions as a tumour suppressor." (PMID 33544460, 2021). "Further, we summarized the underlying mechanisms by which tumor cells develop resistance to anti-tumor therapies, provided theoretical support for targeting USP7 to overcome drug resistance, and some inspiration for the design and development of USP7 inhibitors." (PMID 33967786, 2021). "In summary, we have summarized the underlying mechanisms by which tumor cells develop resistance to anti-tumor therapies, provided theoretical support for targeting USP7 to overcome drug resistance, and further offered some inspiration for the design and development of USP7 inhibitors." (PMID 33967786, 2021). "In addition, in vivo experiments revealed that USP7 inhibition significantly suppressed tumor growth and promoted the expression of apoptotic genes." (PMID 34556124, 2021). "Firstly, despite its major function of USP7 to stabilize oncoproteins, there do exists some exceptions in which USP7 may have a role in cell cycle arrest and tumor suppression." (PMID 33967786, 2021). "Interestingly, besides these tumor suppressors, the proto-oncogenes c-Fos and c-Jun were both upregulated upon USP7 inhibition." (PMID 34518535, 2021). "Substrates of USP7 involved in anti-tumor therapies resistance." (PMID 33967786, 2021). "USP7 functions as an essential role in different cell processes through interacting with its multiple substrates, such as DNA damage and repair, immune responses, epigenetic control, and tumor progression." (PMID 34869041, 2021). "Furthermore, we have also observed that USP7 is closely related to the emergence of anti-tumor drug resistance." (PMID 33967786, 2021). "However, USP7 plays a variety of roles in tumours through the stabilization of different substrates." (PMID 34469054, 2021). "In addition, not only the tumor cell growth was significantly delayed after knocking down USP7, but also the cellular toxicity of paclitaxel and docetaxel but not carboplatin and cisplatin was enhanced significantly." (PMID 32002017, 2020). "However, targeted inhibition of USP7 can increase the expression of PD-L1 in tumor microenvironment, and further combination with PD-1 monoclonal antibody can exert synergistic antitumor effect." (PMID 32802195, 2020).
tumor (continued). "Collectively, two SCCs-associated events (USP7 overexpression and OTUD3 deletion) may cooperate to dampen PTEN tumor suppressor activity." (PMID 32560247, 2020). "To determine whether targeting USP7-mediated anti-tumor immune response is dependent on MΦs, we used clodronate liposomes (Clo) to deplete MΦs from mice." (PMID 32802195, 2020). "Moreover, we found that P5091 (an inhibitor of USP7) was able to activate the systemic anti-tumor T cell immune response." (PMID 32802195, 2020). "Furthermore, we sorted TAMs from mice in the control group and P5091-treated mice by flow cytometry and RNA sequencing analysis to elucidate the molecular mechanism of remodeling tumor TAMs by USP7 targeting." (PMID 32802195, 2020). "A complete understanding of how each individual USP7 function contributes to tumor suppression, however, remains unclear and will require further investigation." (PMID 32850836, 2020). "In addition, interference of ZNF638 or USP7 was able to inhibit migration and invasion of fructose-induced tumor cells." (PMID 33040080, 2020). "Then, we examined the expression of MDM2 and USP7 in MDA-MB-468 xenograft tumor samples." (PMID 32929379, 2020). "Administration of USP7 inhibitors increased the expression of programmed cell death ligand 1 (PD-L1) in tumors, while blocking programmed cell death protein 1 (PD-1) provided an effective anti-tumor response." (PMID 32802195, 2020). "To explore whether targeting USP7 can activate systemic adaptive anti-tumor immunity, we examined the population of CD4+T cells, CD8+T cells, Th1 cells, and CTLs in the spleen." (PMID 32802195, 2020). "Altogether, USP7 appears to play a negative regulatory role in anti-tumor immunity in human LUAD." (PMID 32802195, 2020). "Finally, the role of USP7/hnRNPA1/miR-522 axis in affecting tumor growth and chemotherapeutic efficacy were evaluated in vivo." (PMID 32106859, 2020). "In addition to tumor suppressive roles, USP7 also seems to have context-dependent oncogenic functions." (PMID 32850836, 2020). "Then, we have compared the CCDC6/USP7 expression scores to the tumor grade." (PMID 30786932, 2019). "The correlation between USP7 level of tumor tissues and taxane-resistance was evaluated." (PMID 31730000, 2019). "In prostate cancer, high expression of USP7 is directly related to tumor invasion." (PMID 31114498, 2019). "Hence, abrogation of USP7 in APC-mutated CRC suppresses Wnt activation by regaining β-catenin ubiquitination, which leads to the cell differentiation, and inhibits tumor growth." (PMID 31114498, 2019). "We confirmed that targeting USP7 can suppress tumor growth in vivo by inhibiting Wnt activation." (PMID 29045831, 2017). "If the tumor expresses low levels of the protein, we expect it to respond to olaparib; if it expresses high levels of the protein the sensitivity to olaparib can be restored by the addition of the Usp7 inhibitor." (PMID 28653990, 2017). "To determine whether Usp7 is essential in maintaining tumor-like spheroid growth in Apc-mutant organoids, we deleted Usp7 in Apc5 organoids by CRISPR targeting." (PMID 29045831, 2017). "Finally, the Wnt-activating role of USP7 is specific to APC mutations; thus, it can be used as a tumor-specific therapeutic target for most CRCs." (PMID 29045831, 2017).
tumor (continued). "However, despite wide investigation of USP7 inhibitors in tumor therapy, little has been explored with regard to their application in the bone engineering field." (PMID 28807012, 2017). "In tumors that largely rely on up-regulated USP7 activity for survival and growth, the direct anti-tumor (cytotoxic) effect might be dominant; for tumors that depend on Treg cells for immune evasion, USP7 inhibitor mediated Treg suppression may prevail." (PMID 29236775, 2017). "USP7 inhibition significantly suppresses tumor growth of APC-mutated colon cancer cells but does not affect cells with wild-type APC, suggesting that it can be used as a tumor-specific drug target." (PMID 29045831, 2017). "USP7, besides AR, has different substrates including PTEN and CCDC6, a tumor suppressor protein whose deficiency affects DNA repair mechanism by homologous recombination and sensitizes tumor cells to PARP inhibitors treatment." (PMID 28415632, 2017). "Nearly complete inhibition of enzyme activity is usually required for direct anti-tumor effect, but partial inhibition of USP7 may be enough to tilt the balance of immune homeostasis and initiate immune attack on tumor cells." (PMID 29236775, 2017). "Several USP7 inhibitors have shown potent efficacy against tumor cells." (PMID 27780924, 2016). "Together, these data indicate that CDDO-Me inhibits USP7 activity in tumor tissues." (PMID 27780924, 2016). "The regulation of USP7 in tumor cell proliferation seems to be organ-specific." (PMID 25884169, 2015). "USP7 (also known as HAUSP) is a DUB for several tumor suppressors." (PMID 25885523, 2015). "USP7 regulates the turnover of many critical proteins involved in tumor suppression and DNA repair." (PMID 25605410, 2015). "Upregulation of OGT and USP7 has been reported in a number of tumor types." (PMID 26678539, 2015). "By knocking down USP7 expression with shRNA interference, we revealed that lowering USP7 expression could effectively suppress cell growth rate, foci formation in vitro, and tumor formation in vitro and in vivo." (PMID 25519684, 2015). "Additionally, USP7 activity is related to angiogenesis that promotes tumor irroration." (PMID 41157055, 2025). "Therefore, the role of USP7 in tumor cellular energetic deregulation needs further investigation." (PMID 41157055, 2025). "Indeed, tumor proliferation is also influenced by other USP7-mediated interactions." (PMID 41157055, 2025). "Consequently, it is imperative to ascertain whether STS inhibit USP7 expression in tumor cells to potentiate T cell function." (PMID 40365281, 2025). "Indeed, experimental evidence suggests that the presence of USP7 might be disadvantageous for tumor cell survival." (PMID 41157055, 2025). "However, the direct implication of the role of C16orf72/HAPSTR1 amplification in tumor development is complicated by the fact that the USP7 gene is located adjacent to the C16orf72/HAPSTR1 locus, resulting in concurrent amplification of USP7 and C16orf72/HAPSTR1." (PMID 38580884, 2024). "Although existing studies suggest that USP7 may influence the occurrence and development of tumor inflammatory responses by regulating the expression of various inflammation-related factors, the specific molecular mechanisms and signaling pathways still need to be further explored." (PMID 39767641, 2024).